SNORD35A (small nucleolar RNA, C/D box 35A)
Synonyms: U35; RNU35A; RNU35
Gene: Small nucleolar RNA gene on chromosome 19 (49,491,175 to 49,491,260, forward strand). Ensembl gene ENSG00000200259.
Gene Ontology:
Biological process: RNA processing
Cellular component: nucleolus
Homologues: Orthologues: chimpanzee SNORD35A (99% identical), macaque SNORD35A (97% identical), mouse Snord35a (84% identical), guinea pig SNORD35A (80% identical), rabbit SNORD35A (80% identical), pig SNORD35A (79% identical), rat Snord35a (77% identical). Paralogues in human: SNORD35B (71% identical).
Diseases named in the same sentence as SNORD35A in open-access papers:
SNORD35A is named in the same sentence as 5 diseases in open-access papers, as found by Europe PMC text mining. Sharing a sentence is not in itself a finding about the gene and the disease. The quoted sentences say what the papers report.
leukemia (2 papers, 2019 to 2025). A malignant (clonal) hematologic disorder, involving hematopoietic stem cells and characterized by the presence of primitive or atypical myeloid or lymphoid cells in the bone marrow and the blood. "However, other snoRNAs have been shown to act more like oncogenes: indeed, SNORD14D or SNORD35A are required for leukemia development in vivo in certain models." (PMID 31039818, 2019).
carcinoma (1 paper, 2018). A malignant tumor arising from epithelial cells. "For example, SNORD32, SNORD33A, and SNORD35A although expressed from the same host gene RPL13A are differentially modulated in different carcinomas." (PMID 30577491, 2018).
SNORD35A also shares sentences with these, for which no sentence is quoted: glioblastoma (1 paper); laryngotracheitis (1); Mitochondrial myopathy (1).